DCLK1 (doublecortin like kinase 1)
Description:
Probable kinase that may be involved in a calcium-signaling pathway controlling neuronal migration in the developing brain. May also participate in functions of the mature nervous system.
Synonyms: DCAMKL1; DCDC3A; KIAA0369; DCLK; CL1; CLICK1
Tractability: Small molecule: a structure with a bound ligand is known; a high-quality ligand is known; it belongs to a druggable protein family. Antibody: its Gene Ontology location is reachable by antibodies, with high confidence. PROTAC: ubiquitination databases record sites on it; its protein half-life has been measured; a small molecule that binds it is known.
Target class: CAMK protein kinase DCAMK1 family; Kinase; CAMK protein kinase group; Enzyme; Protein Kinase
Chemical probes: DCLK1-IN-1 (high quality)
Gene: Protein-coding gene on chromosome 13 (35,768,652 to 36,132,164, reverse strand). Ensembl gene ENSG00000133083.
Subcellular location (Human Protein Atlas): Nucleoplasm; Cytosol
Gene Ontology:
Molecular function: protein binding; protein kinase activity; protein serine/threonine kinase activity; ATP binding; protein serine kinase activity
Biological process: response to virus; axon extension; central nervous system development; endosomal transport; nervous system development; protein phosphorylation; intracellular signal transduction
Cellular component: cytoplasm; plasma membrane
Genetic constraint (gnomAD): Loss-of-function variants: 15 observed, 74.6 expected, observed/expected ratio (o/e) 0.2, 90% interval 0.13 to 0.31. The upper end of that interval is the gene's LOEUF score, 0.31, which puts it in group 1 of 6, group 1 being the genes least tolerant of losing a copy. Missense variants: 573 observed, 932.63 expected, observed/expected ratio (o/e) 0.61, 90% interval 0.57 to 0.66. Synonymous variants: 361 observed, 371.7 expected, observed/expected ratio (o/e) 0.97, 90% interval 0.89 to 1.06.
Homologues: Orthologues: chimpanzee DCLK1 (100% identical), guinea pig DCLK1 (99% identical), rabbit DCLK1 (99% identical), mouse Dclk1 (98% identical), rat Dclk1 (98% identical), macaque DCLK1 (94% identical), dog DCLK1 (94% identical), pig DCLK1 (93% identical), tropical clawed frog dclk1 (91% identical), zebrafish dclk1b (82% identical), zebrafish dclk1a (77% identical). Paralogues in human: DCLK2 (68% identical), DCLK3 (31% identical), MYLK3 (21% identical), PNCK (19% identical), CAMK1D (19% identical), CAMK1 (18% identical), CAMKK2 (18% identical), CAMK2D (18% identical), CAMK2G (18% identical), CAMK1G (18% identical), CAMK2B (18% identical), PSKH1 (18% identical), and 10 more.
Diseases named in the same sentence as DCLK1 in open-access papers:
DCLK1 is named in the same sentence as 145 diseases in open-access papers, as found by Europe PMC text mining. Sharing a sentence is not in itself a finding about the gene and the disease. The quoted sentences say what the papers report.
pancreatic cancer (78 papers, 2013 to 2025). "DCLK1 has also been associated with drug resistance in colorectal cancer, pancreatic cancer, and kidney cancer." (PMID 33515271, 2021). "Along with this finding in the mouse model, in human pancreatic cancer tissue, high DCLK1 or POU2F3 levels are associated with a shorter median survival time of patients." (PMID 33022971, 2020). "A recent study reported that DCLK1 regulates the level of PD-L1 expression by affecting the corresponding expression level of yes-associated protein (YAP) in the Hippo pathway in pancreatic tumors." (PMID 33348546, 2020). "Similarly, miR-200a has been shown to suppress DCLK1, which is associated with reduced stemness and tumorigenic potential in pancreatic cancer cells." (PMID 38928187, 2024). "Interestingly, silencing DCLK1 caused macrophages to retain the M1 phenotype and abrogated the M2-macrophage ability to enhance aggressiveness and self-renewal in pancreatic cancer cells." (PMID 33348546, 2020). "Moreover, KRAS mutation in Dclk1+ pancreatic epithelial cells leads to pancreatic cancer in the presence of induced pancreatitis." (PMID 33348546, 2020). "To date, widespread DCLK1 upregulation has been reported across various solid malignancies, including colorectal cancer, breast cancer, pancreatic cancer, renal cancer, as well as hepatocellular carcinoma and esophageal squamous cell carcinoma." (PMID 40775208, 2025). "DCLK1 directly marks cancer stem cells in colon cancer, pancreatic cancer, and cholangiocarcinoma, promotes CSC-like properties and drives cancer initiation, progression, and metastatic spread." (PMID 40775208, 2025). "By conducting a series of carefully planned experiments using mouse models of pancreatic cancer and pancreatic cancer cell lines, our understanding of the role of Dclk1 in cancer has been significantly expanded." (PMID 38892399, 2024). "Regulate cluster cell development and stem cell characteristics of pancreatic cancer cells by increasing the expression of DCLK1, POU2F3, ALDH1A1, and IL17RC." (PMID 39906741, 2024). "For instance, pancreatic cancer PDOs have provided valuable information about tumor invasion and metastasis, revealing that elevated levels of doublecortin-like kinase 1 (DCLK1) can drive cancer cell migration." (PMID 38835507, 2024). "This is supported by the evidence of miR-1246 expression in pancreatic cancer stem cells, where DCLK1 also plays a role." (PMID 38928187, 2024). "The direct binding of Dclk1 to KRAS protein is the key factor in the activation of MAPK in pancreatic cancer cells, indicating the functional interaction of G9a, DCLK1, and MAPK pathways in KRAS-driven PDAC." (PMID 39839479, 2024). "Dclk1 expression is elevated in human pancreatic cancer samples and early murine pancreatic intraepithelial neoplasias." (PMID 38892399, 2024). "KDM3A mediates the upregulation of doublecortin-like kinase 1 (DCLK1), which is critical for the development and progression of pancreatic cancer during hypoxia." (PMID 36902253, 2023). "Expression of Dclk1 was investigated e.g. in neurons and pancreatic cancer stem cells, while, to our knowledge, expression in cells of the oligodendroglial lineage has not been reported previously." (PMID 37594553, 2023). "DCLK1 is also involved in the initiation of gastrointestinal (GI) tumors, such as intestinal cancer, pancreatic cancer, and cholangiocarcinoma." (PMID 37239162, 2023). "The interconnected roles of these miRNAs and the gene DCLK1 underscore their importance in pancreatic cancer progression." (PMID 38139352, 2023). "Increased expression and activity of DCLK1 can promote various cancers, such as colorectal cancer and pancreatic cancer, and can enhance the clonality, invasiveness, metastasis, and reproducibility of cancer cells." (PMID 37762326, 2023). "For instance, DCLK1 has been found to be upregulated in renal clear cell cancer, pancreatic cancer, and colorectal cancer." (PMID 37887321, 2023).
pancreatic cancer (continued). "As a potential effector of KRAS, DCLK1 contributes functionally to the pathogenesis of pancreatic cancer, and marks quiescent pancreatic progenitor cells of pancreatic origin." (PMID 36569325, 2022). "DCLK1 regulated pluripotency and angiogenesis via regulating mir-145 and miR-200 in pancreatic cancer." (PMID 36250024, 2022). "So far, DCLK1-IN-1 has been shown to be effective in only a subset of patient-derived early stage pancreatic cancer organoid samples that expressed DCLK1-S37." (PMID 34545159, 2021). "The upregulation of glycolysis can promote reactive oxygen species (ROS) production, targeting DCLK1 (doublecortin-like kinase 1) to promote the stem-like phenotype and epithelial–mesenchymal transition of gemcitabine-resistant pancreatic cancer cells." (PMID 33607990, 2021). "Although these reports demonstrate the potential of Dclk1+ cells to form pancreatic tumors under specific conditions, the stem cell dynamics in vivo within established tumors has not been explored." (PMID 33393460, 2021). "Next, we examined the stem cell potential of Dclk1+ PDAC cells in metastatic sites by applying an experimental model of metastatic pancreatic tumors." (PMID 33393460, 2021). "The overexpression of miR-15a in pancreatic cancer cells reduces the expression of BMI-1, and similarly, the overexpression of miR-195 (a member of the miR-15 family) inhibits DCLK1 expression." (PMID 33562727, 2021). "Particularly, KDM3A has been reported to enhance the expression of DCLK1 with the removal of di‐ and mono‐methyl residues from H3K9me2/me1, and their high expression in pancreatic cancer tissues was correlated with shorter survival times of patients." (PMID 33350586, 2021). "According to a recent study, increased expression of DCLK1 assists in hypoxia-induced stemness in pancreatic tumors, initiated by the cooperation between HIF-1α and histone lysine demethylase 3A (KDM3A)." (PMID 34453639, 2021). "It was reported that immune cell-derived IL-17 regulates stem cell features of pancreatic cancer cells by increasing the embryonic stem cell markers doublecortin-like kinase 1 (DCLK1) and ALDH 1 family member A1 (ALDH1A1)." (PMID 34572009, 2021). "KDM3A is increased under hypoxia through pancosphere formation in pancreatic cancer cells, thereby increasing the DCLK1 mRNA level." (PMID 32354028, 2020). "This indicates multiple direct IL-17 effects on pancreatic cancer initiation, including the regulation of growth, PanIN formation, and stem cell properties via the regulation of REG3β, DCLK1, POUF3, ALDH1A1, and IL-17RC." (PMID 33022971, 2020). "A small molecule kinase inhibitor, LRRK2-IN-1, was first reported to regulate DCLK1-mediated stemness and EMT by suppressing DCLK1 kinase activity in colorectal and pancreatic cancer." (PMID 33348546, 2020). "DCLK1 was also reported as a target for crocetinic acid when analyzing pancreatic cancer in vitro and in vivo." (PMID 32756469, 2020). "Hypoxia can also be increased epigenetically by histone lysine demethylase 3A (KDM3A) overexpression in pancreatic cancer cells, which leads to increased expression of DCLK1." (PMID 33348546, 2020). "In the pancreas, DCLK1 is a marker of a population of pancreatic cancer-initiating cells, some of which have morphological and molecular features of gastrointestinal TCs." (PMID 33348546, 2020). "Doublecortin-like kinase 1 (DCLK1) is often overexpressed in pancreatic cancer, and recent studies indicate that DCLK1+ PDAC cells can initiate pancreatic tumorigenesis." (PMID 31467540, 2019). "And in pancreatic cancer, DCLK1 also played an important role in promoting metastasis and predicting survival." (PMID 31223610, 2019). "High DCLK1 expression in normal adjacent tissue of PDAC correlated with poor survival and anti-DCLK1 mAb inhibited pancreatic tumor growth in vivo in mouse models." (PMID 31467540, 2019).
pancreatic cancer (continued). "DCLK1 is strongly linked to KRAS-mutant cancer, as evidenced by its expression in tumor stem-like cells in multiple KRAS-mutant pancreatic cancer mouse models." (PMID 31467540, 2019). "In order to evaluate the effect of targeting DCLK1 in pancreatic cancer tumorigenesis, we utilized a novel mAb (CBT-15G), which differs from CBT-15 which we recently reported in renal cell cancer." (PMID 31467540, 2019). "In totality these findings provide the first proof of concept for DCLK1-targeted mAb therapy against pancreatic cancer." (PMID 31467540, 2019). "Human pancreatic cancer cells (AsPC-1 and MiaPaCa-2) were infected with lentivirus and selected to create stable DCLK1 isoform 2 (alpha-long, AL) overexpressing lines." (PMID 31467540, 2019). "Immunohistochemical analysis including Alcian blue, CK-18, cadhedrin-1, and DCLK1 staining confirmed the PanIN region as a characteristic pancreatic cancer precursor lesion." (PMID 30533257, 2018). "In conclusion, our data provide the first evidence that glycolytic signalling plays a functional role in the maintenance of CSC and the EMT phenotypes via down‐regulation of ROS production and up‐regulation of DCLK1 expression in GR pancreatic cancer cells." (PMID 28244691, 2017). "Collectively, these findings reveal that glycolysis‐related ROS regulate the CSC and EMT phenotypes by targeting DCLK1 in GR cells, suggesting that DCLK1 is a promising target in treating pancreatic cancer." (PMID 28244691, 2017). "To investigate the role of DCLK1 in human pancreatic cancer cells, we adopted a gain-of-function strategy by using KLM1 cells that transiently over-expressed GFP-tagged DCLK1." (PMID 26764906, 2016). "Most recently, DCLK1 has been shown to mark a morphologically distinct subpopulation of cells with stem cell properties in pre-invasive pancreatic cancer." (PMID 26673007, 2016). "DCLK1 is a member of the protein kinase super family and the doublecortin family, and marks colon and pancreatic cancer stem cells." (PMID 27335684, 2016). "Some evidence exists for the potential involvement of axon guidance genes in pancreatic carcinogenesis, and these results are consistent with our finding that highly expressed DCLK1 is closely related to invasion and metastasis in pancreatic cancer." (PMID 26764906, 2016). "Overexpression of DCLK1 led to amoeboid morphology, which promotes the migration of pancreatic cancer cells." (PMID 26764906, 2016). "We have previously demonstrated that DCLK1 is a stem cell marker for both normal pancreatic cells and pancreatic cancer tissues." (PMID 26317547, 2015). "In this regard, it has been shown that the protein Doublecortin Calmodulin-like kinase 1 (DCLK1) marks a morphologically distinct subpopulation of cells with stem cell properties in preinvasive pancreatic cancer." (PMID 26317547, 2015). "DCLK1 is overexpressed in pancreatic cancer and correlated to pancreatic intraepithelial (PanIN) stage." (PMID 25723399, 2015). "DCLK1 specifically marks colon/pancreatic cancers in mice, and is expressed by human colon adenocarcinomas (hCRCs)." (PMID 26447334, 2015). "Strong DCLK1 expression was found in ductal epithelial cells and intervening stromal elements in pancreatic cancer (purple staining)." (PMID 25723399, 2015). "We previously demonstrated that DCLK1 post-transcriptionally regulates pluripotency factors via miR-143/145 in pancreatic cancer." (PMID 26468984, 2015). "Targeting DCLK1 arrested colorectal and pancreatic tumor xenograft growth via inhibition of EMT, pluripotency, and critical oncogenic pathways." (PMID 26468984, 2015). "In animal models with xenografted colon and pancreatic tumors, the silencing of the Dclk1 gene resulted in a decrease in tumor size." (PMID 26622789, 2015). "DCLK1 knockdown has previously been shown to reduce the invasive capabilities of pancreatic cancer cells." (PMID 25605241, 2015).
pancreatic cancer (continued). "Since stromal elements are mainly mesenchymal cells, these data suggest that DCLK1 expression is upregulated in both epithelial and mesenchymal cells of pancreatic tumor microenvironment." (PMID 25723399, 2015). "We also assessed the DCLK1 expression in stromal and epithelial compartments in pancreatic tumor tissues." (PMID 25723399, 2015). "DCLK1 mark morphologically distinct and functionally unique population of pancreatic cancer-initiating cells." (PMID 25906749, 2015). "We found Inflammation in the early stages of pancreatic tumor progression and we also observed DclK1 expression as early as 2 months of age in the PDAC GEM." (PMID 25906749, 2015). "siRNA-mediated knockdown of DCLK1 in the AsPC-1 pancreatic cancer cell line results in inhibition of epithelial-to-mesenchymal transition (EMT) and oncogenic targets through induction of tumor suppressor miRNAs let-7a and miR-144 and EMT-inhibitor miR-200a." (PMID 24885928, 2014). "The inhibition of invasiveness of pancreatic cancer cells was observed in the invasion assay following the knockdown of DCLK1." (PMID 24040120, 2013). "Inhibition of multiple oncogenic pathways following the knockdown of DCLK1 was also observed in BxPC-3, human pancreatic cancer cell line." (PMID 24040120, 2013). "Previous studies have demonstrated that DCLK1 is overexpressed in human pancreatic cancer tissues and co-localizes with SNAIL and SLUG." (PMID 24040120, 2013). "Here, we observed downregulation of c-MYC and KRAS via let-7a in AsPC1 tumor xenografts following the knockdown of DCLK1 (a similar mechanism was previously demonstrated in pancreatic cancer cells)." (PMID 24040120, 2013). "Overall, these data taken together demonstrate a potential regulatory role for DCLK1 in the expression of iPSC factors in pancreatic cancers via miR-145 miRNA." (PMID 24040120, 2013). "Our data suggest that by down-regulating DCLK1 expression in pancreatic cancer, we are directly inducing or facilitating upregulation of several endogenous miRNAs within the tumors." (PMID 24040120, 2013). "We also observed a subsequent reduction of miR-200 downstream targets ZEB1 and ZEB2, SNAIL and SLUG following the knockdown of DCLK1 in pancreatic tumor xenografts." (PMID 24040120, 2013). "In the last decades, it has been discovered that certain malignant neoplasms have increased expression of DCLK1, including pancreatic cancer, Esophageal squamous cell carcinoma (ESCC), Renal clear cell carcinoma (RCC), stomach adenocarcinoma (STAD) and colorectal cancer (CRC)." (PMID 38980538, 2024). "In pancreatic cancer, inhibition of DCLK1 could down-regulate PD-L1 expression by regulating YAP in the Hippo pathway." (PMID 38980538, 2024). "IL-17 could also regulate cluster cell development and stem cell characteristics of pancreatic cancer cells by increasing the expression of DCLK1, POU2F3, ALDH1A1, and IL17RC." (PMID 39906741, 2024). "Hence, IL-17 regulates the development of stem cell features of pancreatic cancer cells by increasing the expression of DCLK1, ALDH1A1, and other stem cell markers." (PMID 39839479, 2024). "MicroRNAs and small-molecule inhibitors of DCLK1, LRRK2-IN-1, and DCLK1-IN-1 show promise against colorectal and pancreatic cancer cells in vitro, and DCLK1-targeting CAR-T cell (chimeric antigen receptor T cell) immunotherapy reduces tumor growth in murine models of colorectal cancer." (PMID 37863104, 2024). "Moreover, KRAS mutant Dclk1+ cells can functionally contribute to the pathogenesis of pancreatic cancer and, therefore, are a potential target in cancer treatment." (PMID 37887321, 2023). "Our previous study pointed out that DCLK1 affected antitumor immunity in pancreatic cancer." (PMID 37069669, 2023). "Moreover, DCLK1 silencing by microRNA-195 can downregulate RhoA expression in pancreatic cancer cells, indicating that DCLK1 also has an interaction with RhoA." (PMID 36369000, 2022). "DCLK1 regulates PD-L1 expression in pancreatic tumor via the Hippo pathway." (PMID 36369000, 2022).